TRGV4 (T cell receptor gamma variable 4)
Description:
V region of the variable domain of T cell receptor (TR) gamma chain that participates in the antigen recognition. Gamma-delta TRs recognize a variety of self and foreign non-peptide antigens frequently expressed at the epithelial boundaries between the host and external environment, including endogenous lipids presented by MH-like protein CD1D and phosphoantigens presented by butyrophilin-like molecule BTN3A1. Upon antigen recognition induces rapid, innate-like immune responses involved in pathogen clearance and tissue repair. Binding of gamma-delta TR complex to antigen triggers phosphorylation of immunoreceptor tyrosine-based activation motifs (ITAMs) in the CD3 chains by the LCK and FYN kinases, allowing the recruitment, phosphorylation, and activation of ZAP70 that facilitates phosphorylation of the scaffolding proteins LCP2 and LAT. This lead to the formation of a supramolecular signalosome that recruits the phospholipase PLCG1, resulting in calcium mobilization and ERK activation, ultimately leading to T cell expansion and differentiation into effector cells. Gamma-delta TRs are produced through somatic rearrangement of a limited repertoire of variable (V), diversity (D), and joining (J) genes. The potential diversity of gamma-delta TRs is conferred by the unique ability to rearrange (D) genes in tandem and to utilize all three reading frames. The combinatorial diversity is considerably increased by the sequence exonuclease trimming and random nucleotide (N) region additions which occur during the V-(D)-J rearrangements.
Synonyms: TCRGV4; V1S4
Gene: T-cell receptor variable (V) gene on chromosome 7 (38,353,715 to 38,354,517, reverse strand). Ensembl gene ENSG00000211698.
Subcellular location: Cell membrane
Gene Ontology:
Cellular component: plasma membrane
Homologues: Orthologues: mouse Trgv7 (47% identical). Paralogues in human: TRGV2 (92% identical), TRGV1 (80% identical), TRGV3 (77% identical), TRGV8 (77% identical), TRGV5 (75% identical), TRGV11 (25% identical), TRGV10 (23% identical), TRGV9 (23% identical), TRGC1 (0% identical), TRGC2 (0% identical).
Diseases named in the same sentence as TRGV4 in open-access papers:
TRGV4 is named in the same sentence as 2 diseases in open-access papers, as found by Europe PMC text mining. Sharing a sentence is not in itself a finding about the gene and the disease. The quoted sentences say what the papers report.
tumor (3 papers, 2023 to 2024). "TRGV4 transcripts were more abundant than TRGV9 transcripts within the same tumor, indicating that Vγ4+Vδ1+ cells, which reflect colonic IEL, are on aggregate more abundant than Vγ9+Vδ2+ cells, which are typical of peripheral blood." (PMID 37309673, 2023). "The expression of Trgv1, the gene encoding T cell receptor Vγ1 chain, but not Trgv4, Trgv5, Trgv6 or Trgv7 was also upregulated in tumours of Vil Apc Dock2 mice." (PMID 39242821, 2024).
TRGV4 also shares sentences with these, for which no sentence is quoted: prostate tumors (1 paper).